RARA (retinoic acid receptor alpha)
Description:
Receptor for retinoic acid. Retinoic acid receptors bind as heterodimers to their target response elements in response to their ligands, all-trans or 9-cis retinoic acid, and regulate gene expression in various biological processes. The RXR/RAR heterodimers bind to the retinoic acid response elements (RARE) composed of tandem 5'-AGGTCA-3' sites known as DR1-DR5. In the absence of ligand, the RXR-RAR heterodimers associate with a multiprotein complex containing transcription corepressors that induce histone deacetylation, chromatin condensation and transcriptional suppression. On ligand binding, the corepressors dissociate from the receptors and associate with the coactivators leading to transcriptional activation. Formation of a complex with histone deacetylases might lead to inhibition of RARE DNA element binding and to transcriptional repression. Transcriptional activation and RARE DNA element binding might be supported by the transcription factor KLF2. RARA plays an essential role in the regulation of retinoic acid-induced germ cell development during spermatogenesis (By similarity). Has a role in the survival of early spermatocytes at the beginning prophase of meiosis (By similarity). In Sertoli cells, may promote the survival and development of early meiotic prophase spermatocytes (By similarity). In concert with RARG, required for skeletal growth, matrix homeostasis and growth plate function (By similarity). Together with RXRA, positively regulates microRNA-10a expression, thereby inhibiting the GATA6/VCAM1 signaling response to pulsatile shear stress in vascular endothelial cells. In association with HDAC3, HDAC5 and HDAC7 corepressors, plays a role in the repression of microRNA-10a and thereby promotes the inflammatory response.
Synonyms: RAR-alpha; NR1B1; RAR; RARalpha
Tractability: Small molecule: an approved drug acts on it; a structure with a bound ligand is known; a high-quality ligand is known; it has a high-quality binding pocket; it belongs to a druggable protein family. Antibody: its Gene Ontology location is reachable by antibodies, with high confidence. PROTAC: it is named in the literature on targeted protein degradation; UniProt records ubiquitination sites on it; ubiquitination databases record sites on it; a small molecule that binds it is known.
Target class: Nuclear hormone receptor subfamily 1 group B member 1; Nuclear hormone receptor subfamily 1; Nuclear receptor; Nuclear hormone receptor subfamily 1 group B; Transcription factor
Chemical probes: CHEMBL133725, Indralin, PD081536, PD081981, PD084776, TAMIBAROTENE
Safety:
Unwanted effects reported when the protein is acted on. In parentheses: how it was acted on, where the effect was seen, and who reports it.
Negative effects on testicular histology and spermatogenesis (inhibition; reproductive; source: Brennan et al. (2024))
Gene: Protein-coding gene on chromosome 17 (40,309,180 to 40,357,643, forward strand). Ensembl gene ENSG00000131759.
Subcellular location: Nucleus; Cytoplasm
Subcellular location (Human Protein Atlas): Nucleoplasm; Actin filaments; Cytosol; Nucleoli
Pathways (Reactome):
Developmental Biology: Activation of anterior HOX genes in hindbrain development during early embryogenesis; Transcriptional regulation of granulopoiesis
Signal Transduction: Signaling by Retinoic Acid; TGFBR3 expression
Gene expression (Transcription): Nuclear Receptor transcription pathway
Metabolism of proteins: SUMOylation of intracellular receptors
Gene Ontology:
Molecular function: alpha-actinin binding; chromatin binding; chromatin DNA binding; DNA-binding transcription factor activity; DNA-binding transcription repressor activity; enzyme binding; nuclear receptor activity; protein binding; protein domain specific binding; protein kinase A binding; protein kinase B binding; retinoic acid binding; retinoic acid-responsive element binding; RNA polymerase II cis-regulatory region sequence-specific DNA binding; RNA polymerase II transcription regulatory region sequence-specific DNA binding; sequence-specific double-stranded DNA binding; signaling receptor binding; transcription coactivator binding; DNA-binding transcription factor activity, RNA polymerase II-specific; DNA binding; heterocyclic compound binding; histone deacetylase binding; mRNA 5'-UTR binding; mRNA regulatory element binding translation repressor activity; sequence-specific DNA binding; and 2 more
Biological process: apoptotic cell clearance; cellular response to estrogen stimulus; cellular response to retinoic acid; mRNA transcription by RNA polymerase II; negative regulation of DNA-templated transcription; negative regulation of granulocyte differentiation; negative regulation of miRNA transcription; negative regulation of tumor necrosis factor production; negative regulation of type II interferon production; positive regulation of binding; positive regulation of cell cycle; positive regulation of cell population proliferation; positive regulation of DNA-templated transcription; positive regulation of interleukin-13 production; positive regulation of interleukin-4 production; positive regulation of interleukin-5 production; positive regulation of T-helper 2 cell differentiation; positive regulation of transcription by RNA polymerase II; protein phosphorylation; response to retinoic acid; retinoic acid receptor signaling pathway; cell differentiation; negative regulation of transcription by RNA polymerase II; cellular response to lipopolysaccharide; female pregnancy; and 18 more
Cellular component: chromatin; cytoplasm; cytosol; nucleolus; nucleoplasm; nucleus; plasma membrane; protein-containing complex; RNA polymerase II transcription regulator complex; transcription regulator complex; dendrite; perinuclear region of cytoplasm
Genetic constraint (gnomAD): Loss-of-function variants: 5 observed, 41.35 expected, observed/expected ratio (o/e) 0.12, 90% interval 0.062 to 0.25. The upper end of that interval is the gene's LOEUF score, 0.25, which puts it in group 1 of 6, group 1 being the genes least tolerant of losing a copy. Missense variants: 390 observed, 621.5 expected, observed/expected ratio (o/e) 0.63, 90% interval 0.58 to 0.68. Synonymous variants: 252 observed, 258.2 expected, observed/expected ratio (o/e) 0.98, 90% interval 0.88 to 1.08.
Homologues: Orthologues: macaque RARA (100% identical), dog RARA (99% identical), pig RARA (99% identical), rabbit RARA (99% identical), rat Rara (98% identical), guinea pig RARA (98% identical), mouse Rara (98% identical), tropical clawed frog rara (87% identical), chimpanzee RARA (82% identical), Drosophila melanogaster EcR (24% identical), Caenorhabditis elegans nhr-19 (21% identical), Caenorhabditis elegans nhr-114 (19% identical), and 180 more. Paralogues in human: RARB (72% identical), RARG (69% identical), RORA (28% identical), RORB (28% identical), RORC (28% identical), NR1D2 (27% identical), THRB (27% identical), NR1D1 (26% identical), PPARA (25% identical), NR1H2 (25% identical), PPARD (25% identical), THRA (25% identical), and 6 more.
Diseases named in the same sentence as RARA in open-access papers:
RARA is named in the same sentence as 225 diseases in open-access papers, as found by Europe PMC text mining. Sharing a sentence is not in itself a finding about the gene and the disease. The quoted sentences say what the papers report.
acute promyelocytic leukemia (684 papers, 2000 to 2026). An aggressive form of acute myeloid leukemia (AML), characterized by arrest of leukocyte differentiation at the promyelocyte stage, due to a specific chromosomal translocation t(15;17) in myeloid cells. "RARα and RARβ are associated with acute promyelocytic leukemia (APL) and squamous cell malignancies, where they play a role in regulating cell proliferation and differentiation." (PMID 40430363, 2025). "The PML::RARA fusion protein is the hallmark driver of Acute Promyelocytic Leukemia (APL) and disrupts retinoic acid signaling, leading to wide-scale gene expression changes and uncontrolled proliferation of myeloid precursor cells." (PMID 36759620, 2023). "Acute Promyelocytic Leukemia is caused by expression of the oncogenic Promyelocytic Leukemia (PML)–Retinoic Acid Receptor Alpha (RARA) fusion protein." (PMID 36880596, 2023). "In an animal model of acute promyelocytic leukemia (APL) the EGCG treatment causes PML/RARα degradation in bone marrow cells." (PMID 37513933, 2023). "The first link between SUMO and cancer is probably related to the oncogenic fusion of PML protein with the retinoic acid receptor alpha (RARα), which causes acute promyelocytic leukemia (APL), and actively involves SUMO in cell transformation." (PMID 35887358, 2022). "In line with this, defective RA/RARα axis downstream to the PML-RARα translocation causes acute promyelocytic leukemia due to a failure of promyelocytes differentiation." (PMID 35269942, 2022). "Acute promyelocytic leukemia (APL) accounts for 10–15% of newly diagnosed acute myeloid leukemias (AML) and is typically caused by the fusion of promyelocytic leukemia with retinoic acid receptor α (RARA) gene." (PMID 35494081, 2022). "PLZF joins to RARα or potentially other partner genes, and the translocation causes leukemias, such as acute promyelocytic leukemia and T-cell acute lymphoblastic leukemia." (PMID 34764413, 2021). "One of the most investigated involves a translocation between the TRIM19 gene (also known as PML) on chromosome 15 and the retinoic acid receptor alpha (RARα) gene located on chromosome 17, which is associated with acute promyelocytic leukemia." (PMID 32226386, 2020). "It has been suggested that 1–2% of acute promyelocytic leukemia (APL) patients present variant rearrangements of retinoic acid receptor alpha (RARα) fusion gene, with the promyelocytic leukaemia zinc finger (PLZF)/RARα being the most frequent." (PMID 32455804, 2020). "RARA gene mutations observed in promyelocytic leukemia can induce the cytoplasmic translocation of the receptor." (PMID 29378601, 2018). "Abnormal expression and function of retinoic acid receptor α (RARα) have been reported to be associated with various cancers including acute promyelocytic leukemia and hepatocellular carcinoma." (PMID 28035062, 2017). "It is often involved in the translocation with the retinoic acid receptor alpha gene associated with acute promyelocytic leukemia." (PMID 23799036, 2013). "The PML gene is often fused with the retinoic acid receptor α (RARA) gene, which is associated with acute promyelocytic leukemia." (PMID 23157318, 2012). "It was originally discovered as being fused with the RARA (retinoic acid receptor alpha) gene in translocations underlying acute promyelocytic leukemias in humans." (PMID 20338044, 2010). "The gene is also involved in the translocation of the retinoic acid receptor alpha gene associated with acute promyelocytic leukemia (APL)." (PMID 20396593, 2008). "GAB2 is likewise overexpressed in many human AMLs with mutations in NPM1 and/or signaling genes, and also in acute promyelocytic leukemia initiated by PML::RARA; the PML::RARA fusion protein may activate GAB2 by directly binding to its 5′ flanking region." (PMID 40773291, 2025).
acute promyelocytic leukemia (continued). "Similar pathogenic fusion genes are found in leukemias, such as AML1 (acute myeloid leukemia-1)-ETO (eight twenty-one), PML (promyelocytic leukemia)-RARα (retinoic acid receptor alpha), and ETV6 (ETS variant transcription factor 6)-RUNX1 (RUNX family transcription factor 1)." (PMID 40584293, 2025). "A reduced transcriptional transactivation response to RA was previously demonstrated for RARA constructs encoding p.Gly289Arg in the context of somatically acquired mutation in acute promyelocytic leukemia, but the pathogenic mechanism in a developmental context requires elucidation." (PMID 40519748, 2025). "Acute promyelocytic leukemia (APL) is rarely caused by the PLZF::RARα fusion gene." (PMID 38835381, 2024). "Importantly, it was recently shown that cancer-associated chromosomal translocations, for example the PML/RARα translocation in acute promyelocytic leukemia, or the EML4/ALK translocation in lung cancer, give rise to so-called fusion circRNAs (f-circRNAs)." (PMID 31052302, 2019). "A hallmark of acute promyelocytic leukemia (APL) is the expression of PML/RARα fusion protein." (PMID 31592194, 2019). "HDAC 3 KD in acute promyelocytic leukemia (APL) cells causes restoration of expression of a retinoic acid-dependent gene whose transcription repression was caused by promyelocytic leukemia retinoic acid receptor alpha (PML-RARα)." (PMID 29882797, 2018). "Interestingly, an analogous reciprocal translocation between the RARA with PML (promyelocytic leukemia) genes has been previously associated with the primary cytogenetic abnormality leading to acute promyelocytic leukemia." (PMID 28851357, 2017). "The PML/RARA fusion gene, a characteristic hallmark of acute promyelocytic leukemia (APL), was detected in three patients with acute myeloid leukemia type M3 (AML-M3)." (PMID 40028267, 2025). "Arsenic trioxide (ATO) is able to selectively target and degrade the disease-causing PML::RARα (P/R) oncoprotein in acute promyelocytic leukemia (APL) for curing the disease." (PMID 40330660, 2025). "While acute promyelocytic leukemia (APL) is a well-known subtype with a high risk of DIC due to PML::RARa rearrangements, recent studies have highlighted that non-APL AML also frequently presents with DIC." (PMID 39941313, 2025). "Acute promyelocytic leukemia (APL) is a unique subtype of acute myeloid leukemia (AML) that is characterized by the PML::RARA fusion or, more rarely, a variant RARA translocation." (PMID 36672788, 2022). "Acute promyelocytic leukemia (APL) is caused by a translocation of the retinoic acid receptor alpha (RARα) on chromosome 17, most commonly with the promyelocytic leukemia gene (PML) on chromosome 15, which leads to clonal proliferation of promyeloblasts." (PMID 34485349, 2021). "Retinoids have found a clinical role in the treatment of acute promyelocytic leukemia (APL) (M3 subtype of acute myeloid leukemia), which is associated with translocations involving RARA and which undergo maturation in response to ATRA." (PMID 31805753, 2019). "The RARα isoform is found in the majority of tissues and has been implicated in a number of diseases, most notably acute promyelocytic leukemia (APL)." (PMID 29288071, 2018). "Promyelocytic leukemia cells with promyelocytic leukemia gene and retinoic acid receptor alpha gene (PML::RARA) fusion were noted in his peripheral blood and bone marrow specimens, leading to the diagnosis of APL." (PMID 40310574, 2025). "In APL with fusion gene PML::RARA, miR-15b is described to have an essential function in the proliferation and differentiation of acute promyelocytic leukemia." (PMID 40282406, 2025). "A prototypical example is acute promyelocytic leukemia, which is caused by the PML–RARα fusion gene, a product of the recombination between the promyelocytic leukemia (PML) gene and the retinoic acid receptor-α (RARα) gene." (PMID 40819127, 2025).
acute promyelocytic leukemia (continued). "APL with PML‐RARA fusion, a distinct subtype of acute myeloid leukemia (AML), is characterized by the presence of the promyelocytic leukemia‐retinoic acid receptor alpha (PML‐RARA) fusion gene." (PMID 40251942, 2025). "Among them, three patients with M3 (acute promyelocytic leukemia) were detected with PML/RARA fusion genes, and four patients showed multiple chromosomal structure and quantity abnormalities." (PMID 40028267, 2025). "Our results demonstrate that HGF increases NRP-1 expression by activating the transcription factor RARA, which is a component of the promyelocytic leukemia/RARA oncoprotein." (PMID 40419692, 2025). "qPCR is the oldest method for molecular MRD, and has been used to follow PML::RARA fusion transcripts in acute promyelocytic leukemia since as early as the 1990s." (PMID 38396825, 2024). "Both HIT and APL were confirmed with serotonin release assay (SRA) and promyelocytic leukemia/retinoic acid receptor alpha (PML-RARA) fusion assay, respectively." (PMID 38800206, 2024). "The pharmacological dosage of ATRA binds to the RARA directly and affects promyelocytic leukemia/retinoic acid receptor α (PML-RARα)." (PMID 38671875, 2024). "The hallmark of acute promyelocytic leukemia (APL) is the presence of the characteristic fusion transcript of the promyelocytic leukemia gene with the retinoic acid receptor α gene (PML::RARA)." (PMID 38539495, 2024). "WHO 2022 has eliminated the requirement of a ≥20% blast count as a diagnostic cut-off should a defining genetic abnormality such as PML/RARA in acute promyelocytic leukemia (APL) and core-binding factor AML (e.g., RUNX1-RUNX1T1, CBFB-MYH11) be present." (PMID 39199685, 2024). "Molecular examination revealed promyelocytic leukemia (PML)-retinoic acid receptor alpha (RARα) fusion protein by reverse-transcription polymerase chain reaction (RT-PCR)." (PMID 39483936, 2024). "Acute promyelocytic leukemia (APL) is a subtype of acute myeloid leukemia defined by a fusion gene transcript called PML::RARA." (PMID 39589180, 2024). "The driver oncogenic fusion protein (PML/RARα) of acute promyelocytic leukemia (APL) is a key factor in initiating APL leukemogenesis." (PMID 39000393, 2024). "This group encompasses acute promyelocytic leukemia (APL) with PML::RARA fusion, which is distinct due to its responsiveness to targeted therapy with all-trans retinoic acid (ATRA) and arsenic trioxide." (PMID 39538363, 2024). "Acute promyelocytic leukemia (APL) is an aggressive subtype of acute myeloid leukemia (AML) in which the PML/RARα fusion protein exerts oncogenic activities by recruiting repressive complexes to the promoter of specific target genes." (PMID 36536122, 2023). "Examples include tyrosine kinase inhibitors (TKI) in chronic myelogenous leukemia (CML) that block BCR::ABL1 kinase activity and differentiation therapy with all-trans retinoic acid (ATRA) in acute promyelocytic leukemia (APL) targeting the (PML::RARA) fusion." (PMID 37699001, 2023). "During the development of acute promyelocytic leukemia (APL), the aberrant phase separation of PML/RARα caused by neddylation of the RARα moiety results in the failure of PML nuclear body (NB) assembly, which is essential for tumor suppression." (PMID 37299568, 2023). "In fact, the sequence of IRF2BP2 has an oncogenic role when it fuses with the RARA gene, previously reported in patients with promyelocytic leukemia." (PMID 37876937, 2023). "There has been evidence implicating aggrephagy in autophagic degradation of aggregated oncoproteins in acute leukemia, such as promyelocytic leukemia (PML) retinoic acid receptor alpha (RARA) fusion protein degradation via p62-mediated aggrephagy." (PMID 37180758, 2023). "Acute promyelocytic leukemia (APL) pathogenesis is based on RARA gene translocations, which are of high importance in the diagnosis of and proper therapy selection for APL." (PMID 36980947, 2023).